CEACAM5 (CEA cell adhesion molecule 5)
Diseases named in the same sentence as CEACAM5 in open-access papers (continued):
Sharing a sentence is not in itself a finding about the gene and the disease.
tumor (continued). "The specific binding of NEO-201 to tumor-associated variants of CEACAM5 and CEACAM6 could be due to post-translational modifications (i.e., attachment of O-glycans to the protein structure of those proteins) occurring during the process of carcinogenesis." (PMID 36291783, 2022). "Immune checkpoint blockade of CEACAM5, which synergizes with inhibition of those regulatory pathways, may improve the efficacy of precision immunotherapy targeting tumour heterogeneity caused by cancer stem cells." (PMID 36494785, 2022). "The fact that NEO-201 recognizes tumor-associated variants of CEACAM-5 and CEACAM-6 could be due to the post-translational modifications (i.e., glycosylation) occurring during the process of carcinogenesis." (PMID 35804808, 2022). "CEACAM5 expression level can estimate the presence of micrometastatic cells in lymph node with greater precision than current staging method used for assessing tumor recurrence risk." (PMID 33791201, 2021). "We also identified a large number of cell adhesion and cell communication pathway genes, such as CDH3, SPP1, SPINK and CEACAM5 that are highly up-regulated in all lung AC tumours, and hence could be associated with the early metastasis of lung AC." (PMID 22369099, 2011). "This study suggests that NEO-201 could be a good anti-glycan mAb for the treatment of different types of cancers not only expressing core 1 and/or extended core 1 O-glycans attached to the tumor-associated variant of CEACAM5 and CEACAM6 but also to other tumor-associated proteins." (PMID 36291783, 2022). "Furthermore, delayed-onset respiratory toxicity has been confirmed in clinical trials using CAR T cells targeting carcinoembryonic antigen related cell adhesion molecule 5 (CEACAM5), and on-target off-tumor toxicity has become a concern when tumor-associated antigens are targeted." (PMID 32858947, 2020). "Eleven potential tumor targets were identified, including CEACAM5, TMPRSS4, COL17A1, CLDN18, and AQP5." (PMID 40379788, 2025). "CEACAM5 is broadly utilized as a tumor marker in clinical settings, particularly for colorectal cancer." (PMID 39813112, 2025). "Following the recently described 4-1BBL antibody fusion protein design, different CEA-4-1BBL antibody fusion proteins were generated using five different human CEACAM5-specific antibodies for tumor targeting." (PMID 41283511, 2025). "The expanding landscape of ADC targets in CRC now includes not only antigens on bulk tumor cells (CEACAM5, HER2), but also those on cancer stem cells (LGR5) and critical stromal components (CEACAM6), offering multiple avenues to dismantle the tumor ecosystem." (PMID 41256852, 2025). "For cancer mortality, it identified proteins involved in tumour proliferation and microenvironment modulation (CEACAM5, KRT19 and SDC1), demonstrating COMET’s capacity to uncover meaningful molecular mechanisms." (PMID 40008295, 2025). "Building on these results, the subsequent aim of our study was to develop a novel anti-CEACAM5 antibody conjugated with an NIR fluorophore for real-time tumor tissue identification during surgical procedures, which we designated CMG." (PMID 40868067, 2025). "CEACAM5 expression has been shown to be important for metastasis in colon cancer, but also for immune evasion of tumor cells." (PMID 41283511, 2025). "We provide a comprehensive overview of the ADC landscape, examining key targets on bulk tumor cells (CEACAM5, HER2), cancer stem cells (LGR5, GPR56), and stromal components." (PMID 41256852, 2025). "Consistent with our findings, high CEACAM5 expression in GC tissues was reported, together with a good discrimination capacity between HM and tumor tissues." (PMID 40868067, 2025). "Binding of tusamitamab ravtansine to CEACAM5-expressing tumor cells leads to the internalization of the complex into endosomes." (PMID 40413667, 2025).
tumor (continued). "CEACAM5 is markedly overexpressed (≥50% of tumour cells) in epithelial-derived carcinomas, with the highest prevalence in gastrointestinal malignancies (70–90% of colorectal, 50–70% of gastric, and 40–60% of pancreatic cancers)." (PMID 40725089, 2025). "Altogether, to our knowledge, this is the first anti-CEACAM5 VHH that demonstrated specific tumor uptake in vivo." (PMID 40358697, 2025). "Tusamitamab ravtansine has demonstrated anti-tumor activity in CEACAM5-expressing tumor cell lines and patient-derived xenograft mouse models." (PMID 40413667, 2025). "CEACAM5 overexpression inhibits anoikis, leading to the disruption of tissue architecture and therefore promoting tumor growth and metastasis formation, exemplified by its overexpression in lung metastases derived from breast cancer." (PMID 40358697, 2025). "Due to its broad and relatively tumor-selective expression, CEACAM5 has a high potential to serve as a target for different antibody-based cancer (immuno-) therapies." (PMID 41283511, 2025). "For example, patritumab deruxtecan, a HER3-directed ADC, has shown promising efficacy in EGFR-mutated NSCLC, while tusamitamab ravtansine, targeting CEACAM5, has demonstrated anti-tumor activity in preclinical models and early-phase studies." (PMID 41184856, 2025). "This discriminatory ability was preserved in the patient-derived organoid model, further validating CEACAM5 as a robust tumor-specific biomarker." (PMID 40868067, 2025). "Analysis of the positive pixel was carried out to quantify the signals associated with CLDN4 and CEACAM5, revealing that CLDN4 expression was significantly higher in tumor samples compared to surrounding healthy tissues from the same patients (p < 0.5)." (PMID 40868067, 2025). "Critically, translational validation in advanced mCRPC cohorts confirms serum CEA levels as clinically important correlates of tumor CEACAM5 expression, particularly in NEPC cases." (PMID 40746825, 2025). "This ensures more potent overall actions against CEACAM5/6 positive cells, even if one of these targets is missing on a percentage of cancer cells due to heterogeneity of the tumor." (PMID 38279989, 2024). "While the control mice showed increased tumor volumes with time, CEACAM5 Ab labelled, drug loaded exosome-treated mice showed significant regression of LuCaP145.1 tumors (P = 0.011*)." (PMID 38307935, 2024). "NILK-2401 induced dose-dependent antibody-dependent cellular cytotoxicity (ADCC) of all CEACAM5-positive tumor cell lines tested, with EC50 ranging from 0.04 nM (LS174T) to 0.25 nM (SNU-16)." (PMID 38720892, 2024). "The κλ body platform was used to generate a human CEACAM5xCD47 BsAb selectively blocking CD47 on CEACAM5-positive tumor cells." (PMID 38720892, 2024). "The higher binding affinity to CEACAM5 as compared to CD47 enables the selective blockade of CEACAM5-expressing tumor cells." (PMID 38720892, 2024). "Box plots showed that the expression of LYZ, LCN2, and CEACAM5 from external datasets was significantly higher in tumor samples compared to normal samples (p < 0.01), complementing our findings." (PMID 39456726, 2024). "Results showed that the average CEACAM5 promoter methylation percentage in the tumor part was 17% ± 6%, whereas that of a matched adjacent normal part was 20% ± 3% (p < 0.001)." (PMID 37942534, 2024). "LCN2, a confirmed oncogene in CRC, and CEACAM5, a common tumor marker in CRC diagnosis and treatment, both showed significantly increased expression along the continuum (p < 0.05)." (PMID 39456726, 2024). "The ADC target protein CEACAM5 showed tumor gene and protein expression mainly confined to the early stages I and II." (PMID 38730739, 2024). "NILK-2401 eliminates CEACAM5-positive tumor cell lines (3/3 colorectal, 2/2 gastric, 2/2 lung) with EC50 for antibody-dependent cellular phagocytosis and antibody-dependent cellular cytotoxicity ranging from 0.38 to 25.84 nM and 0.04 to 0.25 nM, respectively." (PMID 38720892, 2024).
tumor (continued). "The MoA of cibisatamab is based on the simultaneous binding of cibisatamab to CEA/CEACAM5 on tumor cells and to the CD3ε chain on T cells, which results in T-cell activation and subsequent tumor cell killing." (PMID 38881900, 2024). "While it is already known that CEACAM5 is highly expressed in multiple tumor types, with lower expression levels in primary epithelial cells, the role of CEACAM6 is less established, although prognostic value has been demonstrated." (PMID 38502695, 2024). "NILK-2401 induced significant dose-dependent phagocytosis of all CEACAM5-positive tumor cell lines tested with EC50 ranging from 0.38 nM (SNU16) to 25.84 nM (H2122), as compared to an isotype control." (PMID 38720892, 2024). "indicate that CEACAM5 overexpression can promote tumour growth through the EMT pathway in the localized regions of aggressive cancer." (PMID 38647235, 2024). "We observed radioactive signals within LuCaP145.1 tumors in CEACAM5 antibody tagged mice showing the specific tumor uptake of these exosomes." (PMID 38307935, 2024). "Carcinoembryonic antigen (CEA), a glycoprotein and tumor marker encoded by CEACAM5, is elevated in patients with CRC." (PMID 39199569, 2024). "Upon CD44 kd, tumor angiogenesis was increased in the paranecrotic areas, accompanied by reduced hypoxia‐inducible factor‐1α and CEACAM5 but increased E‐cadherin expression." (PMID 37849446, 2024). "Both CEACAM5 and CEACAM6 are tumor-associated antigens that play important roles in cell adhesion and tumor cytochemical sensitivity." (PMID 38796667, 2024). "CEACAM5 is far less expressed with respect to the transcript level in total, yet with similar gene expression levels over all tumor stages." (PMID 38730739, 2024). "DIA 12.3 exhibited some cross-reactivity to CEACAM5, a tumor marker with high sequence homology to the N-terminal domain of CEACAM1." (PMID 38346003, 2024). "In contrast, the observed gastrointestinal toxicity likely represents an off-tumour/on-target effect of cibisatamab, targeting normal colonic mucosa, which is known to express high levels of CEACAM5." (PMID 38750034, 2024). "CEACAM5, one of the most widely used tumor markers, belongs to the CEACAM family that comprises 12 closely related proteins in humans." (PMID 38720892, 2024). "CEACAM5 has a significant clinical role as a tumor marker for several tumors including gastrointestinal and respiratory malignancies." (PMID 36741860, 2023). "In a subsequent dose-expansion study in patients with heavily pretreated NSCLC, 20% of patients with high CEACAM5 expression (intensity ≥2+ in ≥50% of tumor cells) had a partial response, and almost half of those patients maintained the response for 1 year." (PMID 37645622, 2023). "CEACAM5 expression at intensity 2+/3+ in <50%, 50%–80%, and ≥80% of tumor cells was observed in 33.3%, 18.5%, and 48.1% of patients in cohort Q2W-LD and 25.0%, 25.0%, and 50.0% of patients in cohort Q3W, respectively." (PMID 37645622, 2023). "Intriguingly, we made an interesting finding that the accumulation of CEACAM5+/CEACAM6+ ductal cells was associated with poor overall survival in PDAC patients, highlighting the tumor-promoting function of these two ductal cell clusters." (PMID 37612267, 2023). "The detected protein levels of CEACAM5 reflect the challenge of inter- and intra-tumour heterogeneity and the importance of patient individuality." (PMID 36691026, 2023). "SGM-101 localization to pulmonary nodules and its correlation with CEACAM5 glycoprotein expression by the tumor as quantified by tumor and normal pulmonary parenchymal fluorescence." (PMID 36705924, 2023). "To assess NILK-2301 activity and mechanism of action, we first addressed killing of CEACAM5-positive tumor cell lines co-incubated with PBMCs from healthy human donors (containing approximately 50% of CD3+ T-cells) as effector cells." (PMID 38087365, 2023).
tumor (continued). "CEACAM5 leads to angiogenesis, tumor formation, metastasis, modulation of immune cells, and is a wide accepted tumor marker for different tumor entities including neuroendocrine PCa." (PMID 37691945, 2023). "Of the 4 patients who underwent surgical intervention, those with 2+ and 3+ tissue CEACAM5 expression had excellent tumor fluorescence, with a mean (SD) tumor to background ratio of 3.11 (0.45)." (PMID 36705924, 2023). "Specifically, MMP9, MMP13, MMP11, and CEMIP were positively associated with the tumor immune microenvironment, while SLPI, SLC2A1, SERPINB5, HK2, CEACAM6, and CEACAM5 were negatively associated with the tumor immune microenvironment." (PMID 37234801, 2023). "The CEACAM5 density on the CEACAM5-positive tumor cells ranged from 257,000 CEACAM5/cell on SK-CO-1 to 6,5000 CEACAM5/cell on SW1116." (PMID 38087365, 2023). "Of the 4 patients who underwent surgical intervention, those with 2+ and 3+ tissue CEACAM5 expression had excellent tumor fluorescence, with a mean (SD) tumor to background ratio (TBR) of 3.11 (0.45) (eFigures 1 and 2 in Supplement 2)." (PMID 36705924, 2023). "After intravenous administration, tusamitamab ravtansine binds to the extracellular domain of CEACAM5 on tumor cells and is internalized, whereupon the disulfide linker is cleaved with the release of active DM4." (PMID 37645622, 2023). "Here, we compare the anti-tumor efficacy of our CAR-T cells with that of an anti-CEACAM5 ADC being clinically evaluated against NSCLC." (PMID 36923424, 2023). "In an interim analysis of a first in-human study (NCT02187848) in patients with non-squamous NSCLC, SAR408701 showed an objective response rate (ORR) of only 23%, even in patients with ≥ 50% of CEACAM5-expressing tumor cells." (PMID 36923424, 2023). "The κλ body platform was used to generate a human CEACAM5xCD3 TCB selectively targeting CEACAM5 on tumor cells and CD3 on T-cells for the treatment of CEACAM5-positive solid cancers." (PMID 38087365, 2023). "The analogue BDC-2034, targeting CEACAM5, has shown anti-tumor activity in vivo at low dose (0.5 mg/kg), activation of the innate immune system and reprogramming of intra-tumor myeloid, thus supporting its clinical development." (PMID 36650546, 2023). "Based on the previous study, the primary members CEACAM1 and CEACAM7 were recognized as tumor suppressors, while CEACAM5 and CEAMCAM6 were upregulated in almost 50% types of tumors and functioned as oncogenes." (PMID 36759883, 2023). "Binding of NILK-2301 was assessed in the presence of 0.02, 0.05 and 0.1 μg/mL of soluble CEACAM5 for the tumor cell lines SK-CO-1, MKN-45, and H2122." (PMID 38087365, 2023). "CEACAM5 is a known tumour marker specific for MC and analysis identified that corresponding enhancers were enriched in most MC samples." (PMID 37120667, 2023). "Malignant nodules with the highest antigenic concentration of CEACAM5, as demonstrated with immunohistochemical staining, had the highest fluorescence emission compared with the margin of the tumor and normal lung and distant normal lung." (PMID 36705924, 2023). "CAR-T cells also showed a dose-dependent tumor growth inhibition and extended survival in CEACAM5-positive DM4S A549-CEACAM5." (PMID 36923424, 2023). "CEACAM5 is a surface glycoprotein that is involved in cell adhesion, intracellular signaling, and tumor progression." (PMID 37264016, 2023). "NILK-2301 binds CD3ɛ on T-cells with its lambda light chain arm with an affinity of ≈100 nM, and the CEACAM5 A2 domain on tumor cells by its kappa light chain arm with an affinity of ≈5 nM." (PMID 38087365, 2023). "NEO-201 can block the interaction between CEACAM-5 expressed on tumor cells and CEACAM-1 expressed on NK cells to reverse CEACAM-1-dependent inhibition of NK cytotoxicity." (PMID 35804808, 2022). "In summary, we have designed a sensitive, quick, efficient, and affordable paper-based immunoassay nanoplatform for quantitative detection via MEF of CEACAM5 tumor marker." (PMID 36233297, 2022).
tumor (continued). "Here we study its performance against three-dimensional tumor organoids in cocultures with T cells as compared to a higher affinity CEACAM5-CD3 (CEACAM5-TCB) bispecific antibody using time-lapse confocal microscopy." (PMID 35154495, 2022). "CEACAM-5 was initially discovered as an oncofetal antigen found to be produced by epithelial tumor cells in the digestive tract." (PMID 35804808, 2022). "Several studies have shown that binding between CEACAM-1 on NK cells and CEACAM-1 or CEACAM-5 on tumor cells inhibits NK activation signaling mediated by NKG2D." (PMID 35804808, 2022). "The heterophilic interaction between CEACAM5 on tumour cells and CEACAM1 on NK cells has been demonstrated to inhibit NK cell-mediated anti-cancer immunity." (PMID 36494785, 2022). "Interactions between CEACAM5/6 on tumor cells and CEACAM1 on immune cells inhibit immune-mediated cytotoxicity." (PMID 35869114, 2022). "NEO-201 can block the interaction between CEACAM-5 expressed on tumor cells and CEACAM-1 expressed on natural killer (NK) cells to reverse CEACAM-1-dependent inhibition of NK cytotoxicity." (PMID 35804808, 2022). "In the present clinical material, the number of tumor cell-positive LNs was 1.33-fold higher based on CEACAM5 mRNA levels than on histopathological examination." (PMID 34192710, 2021). "We estimated that approximately 65% of cibisatamab and 80% of CEACAM5-TCB reaching the tumour interstitial space is bound to the target." (PMID 34959386, 2021). "Detection of tumor cells in LNs by histopathological examination was compared to estimation of the number of tumor cells by CEACAM5 mRNA levels in 185 LNs from 56 patients with CC." (PMID 34192710, 2021). "Our results show high TCBs uptake and accumulation in the tumour interstitial space, indicated by a total interstitial: plasma concentration ratio of 3- and 5-fold for cibisatamab and CEACAM5-TCB respectively." (PMID 34959386, 2021). "The link between CEACAMs and cancer has been established several years ago with the identification of CEA (CEACAM5) as tumor biomarker, and later with the description of CEACAMs’ role as signal modulators involved in cancer progression and metastasis." (PMID 33509252, 2021). "In particular, CEACAM5 is highly expressed by several tumor types, including CRC, lung and gastric tumors, whereas its expression in normal tissue is limited to columnar absorptive cells." (PMID 33509252, 2021). "The number of tumor cell-positive lymph nodes was 1.33-fold higher based on CEACAM5 mRNA levels compared with histopathological examination." (PMID 34192710, 2021). "Clinically, CEACAM5 is widely used as a marker of tumor progression in colonic malignancies, and an elevation in CEACAM5 levels is generally seen as a sign of a large tumor burden and poor prognosis." (PMID 34394073, 2021). "The number of LNs identified as tumor cell positive by detection of CEACAM5 mRNA was significantly increased when the extract was from half-LNs compared with from 80-μm sections (p < 0.0001)." (PMID 34192710, 2021). "CEA cell adhesion molecule 5 (CEACAM5) is a well-studied biomarker for gastrointestinal cancers and thought to promote tumour development as a cell adhesion molecule." (PMID 34790815, 2021). "Approximately one-fourth of the H&E(–) LNs had POSTN mRNA levels in the range of those in H&E(+) LNs, suggesting that these LNs were affected by tumor cells, which in turn suggests that the LNs with low CEACAM5 levels indeed harbor tumor cells." (PMID 34192710, 2021). "All primary tumor tissues exhibited significantly higher expression of CEACAM5 compared to normal tissues." (PMID 33004987, 2020). "are tumor heterogeneity, in which CEACAM5 expression is selectively diminished by therapy in a subset of tumor cells, or a selective effect of therapy on the cell genome resulting in clonal evolution." (PMID 33004930, 2020).